CD38 (CD38 molecule)
Diseases named in the same sentence as CD38 in open-access papers (continued):
Sharing a sentence is not in itself a finding about the gene and the disease.
sarcoma (4 papers, 2021 to 2024). A usually aggressive malignant neoplasm of the soft tissue or bone. "Conversely, RA treatment was also reported to benefits tumor progression in sarcoma and chronic lymphocytic leukemia (CLL) by promoting the pro-tumoral differentiation of intertumoral monocytes in sarcoma and increasing CD38 expression in CLL cells." (PMID 33889575, 2021). "T‐cells in the sarcoma microenvironment exhibited elevated levels of cytotoxicity (GZMB, GNLY and KLRD1), exhaustion (HAVCR2, CD38, CD160, CXCL13 and CX3CR1), and inflammation (IL33, PPARG, IL6R and SOCS3), suggesting an activated but exhausted phenotype." (PMID 39658531, 2024).
steatosis (4 papers, 2021 to 2025). Increased lipid within the cytoplasm of cells. "CD63, C-Type Lectin Domain Family 1 Member B (CLECB1), CD38, MANF, and Gamma-interferon-inducible lysosomal thiol reductase (IFI30) were all associated with steatosis grade in PWS." (PMID 39407757, 2024). "In this group, CD63 and CD38 positively correlated with steatosis grade, while NCAN and BCAN positively correlated with bioimpedance values." (PMID 39407757, 2024).
triple-negative breast carcinoma (4 papers, 2018 to 2025). An invasive breast carcinoma which is negative for expression of estrogen receptor (ER), progesterone receptor (PR), and human epidermal growth factor receptor 2 (HER2). "A previous retrospective immunohistochemical study demonstrated that tumor-infiltrating IgKC- and CD38-positive B-lymphocytes were associated with better prognosis in patients with early triple-negative breast cancer." (PMID 39456897, 2024). "Analysis of CD38 expression level and survival outcomes in triple negative breast cancers (TNBC) using data from the European Genome–phenome Archive." (PMID 29899747, 2018). "A favorable prognostic significance of tumor-infiltrating plasma cells could be demonstrated in triple-negative breast cancer immunohistochemically analyzed for the CD38 and IgκC expression." (PMID 37894900, 2023). "Similarly, CD38 has been identified as an independent prognostic factor in patients with triple-negative breast cancer, where higher expression of CD38 on tumor-infiltrating plasma cells is associated with increased metastasis-free survival and overall survival." (PMID 40382743, 2025). "Multivariate analysis of intratumoral CD38+ plasma cell and CD20+ B cell density with survival outcomes in triple negative breast cancer (TNBC) patients." (PMID 29899747, 2018).
acute B lymphoblastic leukemia (3 papers, 2016 to 2023). "In B-cell precursor acute lymphoblastic leukemia in children, the presence of CD34+CD38− lymphoblasts at the diagnosis may be considered an unfavorable prognostic factor for disease recurrence." (PMID 37675394, 2023).
acute myocardial infarction (3 papers, 2016 to 2023). Necrosis of the myocardium, as a result of interruption of the blood supply to the area. "Ischemia/reperfusion of the heart causes CD38 activation, and luteolinidin, as a CD38 inhibitor, preserves cardiac function and reduces myocardial infarction size after reperfusion." (PMID 34070757, 2021). "In addition, our unpublished data showed that CD38 deficiency improved the cardiac functions and decreased the death rate of acute myocardial infarction in mice." (PMID 37958991, 2023).
allergic rhinitis (3 papers, 2019 to 2024). Inflammation of the nasal mucous membranes caused by an IgE-mediated response to external allergens. "In addition, some surface molecules have been validated to promote allergic rhinitis flare-ups, such as CD19 on IgD- CD27- B cell, CD25 on IgD+ CD38- B cell." (PMID 39399526, 2024).
atopic dermatitis (3 papers, 2024 to 2025). "Previous studies have reported that NMN supplementation decreases ROS levels by inhibiting CD38 expression, recruits glutathione to repress skin oxidative damage and improves the symptoms of atopic dermatitis in mice by blocking ROS." (PMID 38790612, 2024). "The results indicate a significant decrease in MAIT cells and CD69 subsets in atopic dermatitis, coupled with elevated CD38 and polyfunctional MAIT cells producing TNFα and Granzyme B (TNFα+/GzB+)." (PMID 38542456, 2024). "Vα7.2+/CD161− T cells in atopic dermatitis exhibited a decrease in CD8 and IFNγ-producing subsets but an increase in CD38 activated and IL-22-producing subsets." (PMID 38542456, 2024).
cardiomyopathy (3 papers, 2021 to 2023). A disease of the heart muscle or myocardium proper. "To further investigate the role of CD38 in the development of the cardiomyopathy in mdx mice, we administrated isoproterenol (2.5 mg/kg/d subcutaneously for 10 days) to young mdx mice." (PMID 35298089, 2022). "Since cardiomyopathy is a typical feature of DMD, we next focused on the effect of CD38 deletion in mdx heart dysfunction, knowing that CD38 deletion in WT mice had no impact on cardiac function and structure." (PMID 35298089, 2022). "Isolated B cells from CCD patients with or without cardiomyopathy and non-infected (NI) donors were stimulated with T. cruzi lysate or CpG + CD40L, and characterized by flow cytometry based on the expression of CD24, CD27, CD38, and the regulatory molecules IL-10 and PD-L1." (PMID 34458163, 2021).
chronic endometritis (3 papers, 2021 to 2026). A non-granulomatous or granulomatous chronic inflammation of the endometrium. "The results of the immunofluorescence assay also illustrated a significant presence of TNF-α and CD38 signals in the endometrial tissues of the chronic endometritis group compared to those in the healthy group and the control group." (PMID 34234149, 2021). "The incidence of chronic endometritis was higher in the high-value CD56 group (≥ 23.5 cells/HPF), and in the high-value CD38 group (≥ 0.5 cells/HPF) (χ2 = 15.994, χ2 = 129.067, and both P < 0.001)." (PMID 41756395, 2026). "However, immunohistochemical staining of the postoperative specimens revealed no positive staining for CD38 or CD138, which might not be supposed chronic endometritis." (PMID 37872546, 2023).
coronary atherosclerosis (3 papers, 2016 to 2023). Atherosclerosis of the coronary vasculature. "Several studies by Li PJ and colleagues reported that CD38 gene ablation or inhibition of its activation promotes coronary atherosclerosis." (PMID 36831262, 2023). "The deficiency of this CD38‐associated regulation of lysosome function contributes to the lysosomal cholesterol sequestration in macrophages and coronary atherosclerosis in CD38 −/− mice." (PMID 26818887, 2016). "It has been reported that a defection of the CD38/NAADP signaling pathway leads to lysosomal cholesterol accumulation in macrophages and results in coronary atherosclerosis in CD38−/− mice." (PMID 29977153, 2018).
Cutaneous T-Cell Lymphomas (3 papers, 2022 to 2025). "Reports on the expression of CD38 in Sézary syndrome (SS), erythrodermic primary cutaneous T cell lymphoma with leukemic involvement, are limited." (PMID 35251370, 2022).
diabetic nephropathy (3 papers, 2008 to 2025). "The inverse regulation of SIRT1 and CD38 underscores a dysfunctional NAD+-SIRT1 signaling disruption that undermines mitochondrial resilience in diabetic nephropathy." (PMID 41470091, 2025). "The figure shows the transition from normal physiology to hyperglycemia and diabetic nephropathy, highlighting increased CD38- and PARP1-mediated NAD+ consumption, compensatory NAMPT upregulation, and subsequent SIRT1 depletion leading to mitochondrial dysfunction and renal injury." (PMID 41470091, 2025). "We just speculate that those withanti-CD38 autoantibodies should show lower frequencies of diabetic nephropathy,and other vascular complications in long-term follow-up studies due to betterglycemic control and increased ADPRCA reflecting less maturated PBMCs." (PMID 19300526, 2008).
epilepsy (3 papers, 2021 to 2025). A brain disorder characterized by episodes of abnormally increased neuronal discharge resulting in transient episodes of sensory or motor neurological dysfunction, or psychic dysfunction. "Five feature genes, namely CD38, FAIM2, IL1B, PAWR, and S100A8, were identified as diagnostic biomarkers for epilepsy subtyping, forming the basis for constructing a disease classification model." (PMID 38384278, 2024). "Combining the results of both algorithms, we identified five feature genes (CD38, FAIM2, IL1B, PAWR, S100A8) as diagnostic biomarkers for epilepsy grouping." (PMID 38384278, 2024). "The CD38/cyclic ADP‐ribose (cADPR) pathway is also activated during epilepsy, and the CD38‐induced intracellular calcium elevation may be a critical pathological process in the development of epilepsy." (PMID 40103702, 2025). "Notably, CD38, a transmembrane glycoprotein, emerged as a key player in epilepsy pathogenesis due to its involvement in NAD+ degradation and intracellular calcium ion balance." (PMID 38384278, 2024). "The CD38/cADPR signaling pathway may be a new target for epilepsy treatment." (PMID 40103702, 2025).
gingivitis (3 papers, 2018 to 2024). A disorder involving inflammation of the gums; may affect surrounding and supporting structures of the teeth. "However, they found that memory B cells (CD19+CD27+CD38-) represented the majority in the B cell population in clinically healthy gingiva and in gingivitis tissues (around 90% of the B cell population)." (PMID 29447240, 2018).
gout (3 papers, 2023 to 2024). A condition characterized by painful swelling of the joints, which is caused by deposition of urate crystals. "Western blot analysis of cell lysates of PBMCs from 3 healthy controls and 3 gout patients showed increased CD38 expression in gout patients compared to healthy controls." (PMID 38493256, 2024). "A recent study confirmed CD38 upregulation in gout patients and further validated the role of CD38 in experimental models of gouty inflammation induced by MSU crystals." (PMID 39527634, 2024). "Our analysis revealed some trends in the expression of homing receptors CCR5 and CCR7 as well as CD38 on CD4 T cells in gout patients indicating that the migratory pattern of T cells can be affected." (PMID 37714974, 2023). "Targeting CD38 and NAD+ are potentially novel selective molecular approaches to limit gouty arthritis." (PMID 38493256, 2024). "Seminal studies suggested that gout patients may have lower systemic NAD+ levels and increased PBMC CD38 expression compared to healthy controls." (PMID 38493256, 2024). "In this study, we tested the potential role of therapeutically targeting CD38 and NAD+ in gout." (PMID 38493256, 2024).
Graves disease (3 papers, 2021 to 2025). Graves' disease is an autoimmune disorder that leads to overactivity of the thyroid gland (hyperthyroidism).It is caused by an abnormal immune system response that causes the thyroid gland to produce too much thyroid hormones. "Another study reported elevated levels of a rare subset of CD38-FoxP3+IL-10+ Bregs and decreased levels of CD38+FoxP3+IL-10+ Bregs in pediatric patients with Graves’ disease." (PMID 40458534, 2025). "Presumably, expansion of CD38- B cells with Foxp3+ and/or IL-10 expression counteracts reduced numbers of CD38+Foxp3+IL-10+ Bregs and is a sign of a compensatory mechanism aimed at the reduction in autoimmune reactions related to Graves’ disease." (PMID 34681587, 2021). "Moreover, reduced values for CD38+ cells with co-expression of Foxp3 and IL-10 were reported in Graves’ disease pediatric patients." (PMID 34681587, 2021).
hairy cell leukemia (3 papers, 2021 to 2022). Hairy cell leukemia (HCL) is a rare type of leukemia in which abnormal B-lymphocytes are present in the bone marrow, spleen and peripheral blood. "Similarly, hairy cell leukemia patients with higher CD38 expression were found to have shorter overall survival." (PMID 34211854, 2021). "In hairy cell leukemia, elevated levels of CD38 expression are a marker of a poor prognosis, and CLL patients with high CD38 expression also have more aggressive clinical behaviors and a less optimistic prognosis." (PMID 33820568, 2021).
heart failure (3 papers, 2021 to 2025). Inability of the heart to pump blood at an adequate rate to meet tissue metabolic requirements. "Inhibition of CD38 has been demonstrated to inhibit cardiac hypertrophy and prevent heart failure by activating the SIRT3-FOXO3-mediated antioxidant signalling pathway." (PMID 40507126, 2025). "Finally, this study also potentially concerns other pathologies, such as other dilated cardiomyopathies and heart failure, which combine Ca2+ dysregulation and NAD+ deficit, for which an anti‐CD38 therapy could be highly relevant." (PMID 35298089, 2022).
Hyperglycemia (3 papers, 2008 to 2025). An increased concentration of glucose in the blood. "Our results therefore integrate these molecular events into a coherent model whereby chronic hyperglycemia provokes NAD+ depletion, mitochondrial dysfunction, and fibrosis through converging CD38-NAMPT-SIRT1 perturbations." (PMID 41470091, 2025). "Hyperglycemia-induced oxidative stress is known to activate NAD+-consuming enzymes, particularly CD38." (PMID 41470091, 2025).
hypogammaglobulinemia (3 papers, 2021 to 2024). "Despite the advent of mAbs (e.g., the anti-CD38 mAbs, bi-specific antibodies) having enhanced the overall survival of MM patients, their use has been associated with a higher risk of developing hypogammaglobulinemia and severe infections." (PMID 39335161, 2024). "Several clinical studies have shown that MM patients treated with the anti-CD38 daratumumab, as well as anti-BCMA bi-specific antibodies, may develop severe hypogammaglobulinemia." (PMID 39335161, 2024).
Infertility (3 papers, 2023 to 2025). "Therefore, we studied the incidence of CE and its effect on clinical pregnancy outcome in patients with unexplained infertility through hysteroscopy combined with the detection of CD38 and CD138 in endometrial tissue." (PMID 37391747, 2023). "The cell surface enzyme CD38 is well studied for its role as an NAD+ glycohydrolase in inflammation, infertility, senescence, and ageing, and there is strong interest in the use of small molecule CD38 inhibitors as a strategy to preserve NAD+ levels." (PMID 39894219, 2025). "CD38 and CD138 were detected by hysteroscopy and immunohistochemistry in 145 patients with unknown infertility." (PMID 37391747, 2023).
lentivirus infection (3 papers, 2016 to 2023). Virus diseases caused by the Lentivirus genus. "The importance of CD38 and oxytocin in social memory was further confirmed by local re-expression of human CD38 in the hypothalamus by CD38-containing lentivirus infection or simple subcutaneous supply of oxytocin in CD38 KO mice, in which social behavioral impairment was rescued." (PMID 37215105, 2023). "These phenotypes were rescued by simple subcutaneous injection of OT as well as brain local re-expression of human CD38, but not mutant CD38, by the lentivirus infection method in CD38 knockout mice." (PMID 26586001, 2016). "Taken together, these results demonstrated that the SYK gene was successfully expressed in DCs by lentivirus infection and that SYK-DCs generated in vitro could stimulate naïve T cells to become active and express higher levels of CD3+CD8+, TCRαβ+, CD3+CD38+, and CD3+HLA-DR+ compared with controls." (PMID 29372378, 2018).
leprosy (3 papers, 2011 to 2021). Leprosy is a chronic infectious disease affecting primarily the skin and peripheral nervous system. "In our study, these expression frequencies, especially CD38 on CD8+ T cells, appeared to be associated with viral load because group 3 HIV/leprosy individuals showed the highest activation profile." (PMID 22205964, 2011). "Obviously, the evaluation of the leprosy individuals under reversal reaction need to be conducted, in order to investigate if the CD38 expression on CD8+ T cells will follow the same profile." (PMID 22205964, 2011). "The evaluation of the activation parameters showed high frequencies of HLA-DR expression in CD3+ T cells and CD38+ expression in CD8+ T cells in HIV/leprosy-coinfected individuals, as was previously observed by the present authors in Leishmania/HIV-coinfected patients." (PMID 22205964, 2011). "As for differentiating leprosy per se vs. ODD, genes IDO1, BLK (exon 11), CD38, CXCL11, and SLAMF7, all had an area under the curve (AUC) of at least 96% with their lower bound 97% confidence intervals above 90%." (PMID 34695167, 2021). "We observed a reduced frequency in patients with MB leprosy and with ENL both in total B cells (CD19+) and in memory cells (CD19+CD24+CD38+/-)." (PMID 34621273, 2021). "Indoleamine 2,3-dioxygenase 1 (IDO1) expression alone was highly discriminatory, followed by TLR10, BLK, CD38, and SLAMF7, whereas the HS3ST2 and CD40LG mRNA separated multi- and paucibacillary leprosy." (PMID 34695167, 2021). "Because the expression of these activation markers, especially CD38, correlates strongly with HIV replication and viral load levels, the HIV/leprosy-coinfected individuals were also evaluated according to their different VL levels." (PMID 22205964, 2011).
leukocytosis (3 papers, 2013 to 2025). "CD34+ CD38− phenotype is found in all patients regardless of value and presented poor prognosis factors such as leukocytosis, blasts." (PMID 23667721, 2013).
liver cirrhosis (3 papers, 2020 to 2025). "Despite the lack of a strong correlation between activated T cells and the proportion of TEMRA CD4+ T cells, CD8+ T cells expressing CD38+ were associated with an increase in TEMRA CD4+ T cells in patients with liver cirrhosis." (PMID 39755990, 2025). "Remarkably, we indicated increased percentage of hepatic atMBC and CD27+CD38++plasma cells in ACLF, which was in sharp contrast to liver cirrhosis and HCs." (PMID 36505417, 2022). "A number of co-stimulatory molecules, namely CD40L, OX-40, GITR, and TIM-1 were significantly upregulated on both effector and regulatory CD4+ T cells in patients with liver cirrhosis compared to healthy controls, as well as the T cell activation markers CD69 and CD38." (PMID 33574809, 2020). "Therefore, determining the negative control exerted by the CD38 marker in CD4+ T cell differentiation and the mechanism by which this inhibition impacts the control of tumor cells and bacterial infections is critical in patients with liver cirrhosis." (PMID 39755990, 2025).
measles (3 papers, 2017 to 2022). A highly contagious viral infection caused by the measles virus. "Here, the authors sorted plasma cells into 4 subsets based on CD19/CD38/CD138 expression from healthy adults and performed ELISPOTs to detect vaccine antigen-specific plasma cells for measles, mumps, seasonal influenza, or tetanus toxoid." (PMID 36466924, 2022).
membranous nephropathy (3 papers, 2016 to 2024). "The opposite result showed a positive correlation between CD38+CD19+ B cells and IL-10+CD19+ B cells and hepatitis B virus-associated membranous nephropathy." (PMID 31649905, 2019).
nasopharyngeal carcinoma (3 papers, 2021 to 2023). A carcinoma arising from the nasopharyngeal epithelium. "In a previous study, we reported that CD38 is highly associated with late staging and poor prognosis of nasopharyngeal carcinoma 8-9." (PMID 36605482, 2023). "We also explored the effect of the CD38 gene on the malignant biological behavior of nasopharyngeal carcinoma cells from the point of view of cell proliferation, and discussed its downstream mechanism." (PMID 36605482, 2023). "In some solid tumors, such as nasopharyngeal carcinoma, upregulation of CD38 promoted tumor cell proliferation and metastasis." (PMID 34211854, 2021).